SLC26A4 (solute carrier family 26 member 4)
Diseases named in the same sentence as SLC26A4 in open-access papers (continued):
Sharing a sentence is not in itself a finding about the gene and the disease.
Pendred syndrome (continued). "Variants in SLC26A4 have been linked to syndromic deafness characterized by congenital SNHL and goiter (Pendred syndrome)." (PMID 38410152, 2024). "A genetic cause was found for both subjects (Townes–Brocks syndrome (SALL1) and Pendred Syndrome (SLC26A4))." (PMID 36675424, 2023). "Pathogenic variants in the SLC26A4 gene leading to nonsyndromic recessive deafness (DFNB4), or Pendred syndrome, are some of the most common causes of hearing loss worldwide." (PMID 37107686, 2023). "However, pathogenic variant analysis of the SLC26A4 gene was previously performed in 246 families with HL cases from the Bashkortostan Republic of Russia (Volga–Ural Region) and in 20 patients with Pendred syndrome, EVA, and/or Mondini anomalies in a geographically dispersed sample." (PMID 36499699, 2022). "The solute carrier family 26 member 4 (SLC26A4 or PDS) gene, encoding the protein pendrin, is the causal gene of Pendred syndrome, which is a recessively inherited disorder with hearing loss as the obvious feature." (PMID 35154281, 2022). "Mutations of SLC26A4 cause isolated DFNB4 hearing loss or a combination of congenital hearing loss, balance, and thyroid disorders known as Pendred syndrome." (PMID 35444606, 2022). "Defects in SLC26A4 are among the most frequent causes (up to 10%) of early-onset autosomal recessive hearing loss (arHL); non-syndromic DFNB4 (MIM: 600,791) and Pendred syndrome (MIM: 274,600)." (PMID 34410491, 2022). "The stria vascularis is atrophied and hyperpigmented in the ears of Slc26a4-null mice, a model of Pendred syndrome." (PMID 35185769, 2022). "Solute carrier family 26 member 4 (SLC26A4), encoding pendrin (an anion transporter), causes Pendred syndrome and an enlarged vestibular aqueduct." (PMID 35741772, 2022). "Mutations in the SLC26A4 gene cause nonsyndromic recessive deafness (DFNB4, OMIM 600791) and Pendred syndrome (PDS, OMIM 274600), which combines sensorineural HL and the enlargement of the thyroid glands (goiter)." (PMID 36362242, 2022). "The contribution of biallelic SLC26A4 variants in patients with IP-1, IP-2, IP-2+EVA, and isolated EVA was 66.7% (DFNB4 in three patients, Pendred syndrome in one patient)." (PMID 36499699, 2022). "The phenotypes of SLC26A4-related HL range from nonsyndromic recessive sensorineural HL (DFNB4) to Pendred syndrome with varying onsets with respect to its full clinical manifestation." (PMID 36362242, 2022). "He had a complex phenotype beyond Pendred syndrome presentation, hence, our study reported an ASD child with SLC26A4 variants." (PMID 35741772, 2022). "Mutations in the SLC26A4 gene leading to nonsyndromic recessive deafness (DFNB4) and Pendred syndrome are common genetic causes of hereditary HL, at least in some Asian populations." (PMID 34943614, 2021). "Pathogenic sequence alterations (mutations) or transcriptional dysregulation of a same gene, SLC26A4, can cause non-syndromic EVA as well as EVA in the context of Pendred syndrome and distal renal tubular acidosis with deafness syndrome." (PMID 34562878, 2021). "Mutations in the SLC26A4 gene cause non-syndromic recessive deafness (DFNB4, OMIM 600791) and Pendred syndrome (PDS, OMIM 274600), which combines sensorineural HL and goiter." (PMID 34943614, 2021). "Mutations of SLC26A4 can cause bilateral EVA and a thyroid iodination defect that can lead to multinodular goiter as part of Pendred syndrome (PS) (OMIM 274600)." (PMID 31266487, 2019). "Clinically, SLC26A4 mutations contribute to non-syndromic enlarged vestibular aqueduct (DFNB4, MIM 600791) and Pendred syndrome (PS, MIM 274600)." (PMID 31581539, 2019). "In an additional sample of 15 individuals with suspected Pendred syndrome, because of the presence of hypothyroidism or cochleovestibular malformations, the SLC26A4 gene coding region was also sequenced." (PMID 29739340, 2018).
Pendred syndrome (continued). "The solute carrier family 26, member 4 (SLC26A4), encoding a transmembrane protein, is considered as the second most common responsible gene for NSHL and Pendred syndrome." (PMID 28225033, 2017). "The SLC26A4 (PDS) gene mutations result in abnormalities of the endolymphatic system, which lead to the dilation of the vestibular aqueduct as seen in Pendred syndrome." (PMID 26236732, 2015). "The SLC26A4 gene was first localized and cloned by Everett and colleagues from patients with Pendred syndrome." (PMID 22551242, 2012). "Mutations in the SLC26A4 gene are found in not only patients with Pendred syndrome (PS; OMIM # 274600), but also in individuals afflicted with nonsyndromic hearing loss (NSHL) with enlarged vestibular aqueduct (EVA) at the DFNB4 locus." (PMID 23151025, 2012). "SLC26A4, which is also known as the Pendred syndrome (PDS) gene, is located on human chromosome 7q31." (PMID 22551242, 2012). "SLC26A5 has been implicated in non-syndromic SNHL whereas SLC26A4 gene mutations are associated with both autosomal recessive non-syndromic SNHL (DFNB4) and Pendred syndrome." (PMID 20668687, 2010). "Pathogenic variants in the SLC26A4 gene, encoding for Cl−/HCO3− and I− anion transporter pendrin, are associated with non-syndromic hearing loss with enlarged vestibular aqueduct (NSEVA) and Pendred syndrome (PDS)." (PMID 40426046, 2025). "In this review, SLC26A4-associated HL refers to DFNB4 and Pendred syndromes." (PMID 39609929, 2024). "Variants in SLC26A4 (DFNB4) have been linked to both ARNSHL and Pendred syndrome." (PMID 38534090, 2024). "As no genetic mutation of SLC26A4 was found in our case, we did not test further for Pendred syndrome." (PMID 39493157, 2024). "Here, we describe the first case of Pendred syndrome and non-cystic fibrosis bronchiectasis in a child possibly caused by SLC26A4 mutations." (PMID 36699303, 2023). "Pendred’s syndrome (PDS, OMIM #274600) was confirmed in one patient (autosomal recessive HL with bilateral EVA combined with nodular goiter; patient code 1091) with a homozygous variant c.2027T>A p.(Leu676Gln) in the SLC26A4 gene." (PMID 36499699, 2022). "SLC26A4 has been associated with ARNSHI and Pendred syndrome [(OMIM: 274600)]." (PMID 35440622, 2022). "Biallelic mutations in SLC26A4 lead to Pendred syndrome (OMIM #274600) or non-syndromic deafness DFNB4 (OMIM #600791), both of which are inherited in an autosomal recessive manner." (PMID 34562878, 2021). "Solute carrier family 26 member 4 (SLC26A4) has not yet been reported with a clear role in the thyroid, but it is associated with thyroid dysfunction (Pendred's syndrome)." (PMID 31565069, 2019). "Other described digenic cases include SLC26A4 and FOXI, which causes Pendred syndrome or HI associated with enlarged vestibular aqueducts (EVA) in humans or EVA in the mouse mutant, and SLC26A4 and KCNJ10, which have been observed to cause HI and EVA in humans." (PMID 30029624, 2018). "Two genes, KCNJ10 and FOXI1, have been investigated for their role in the PDS disease spectrum and it has been proposed that digenic mutations in both SLC26A4 and either FOXI1 or KCNJ10 may cause Pendred syndrome." (PMID 23965030, 2013). "SLC26A4 mutations are responsible for Pendred syndrome and non-syndromic enlarged vestibular aqueduct (EVA)." (PMID 23185506, 2012). "Considering the phenotypic variability among patients with SLC26A4 mutations and the difficulty of diagnosing Pendred syndrome, the frequency of sensorineural hearing loss resulting from DFNB4/Pendred syndrome may be underestimated." (PMID 20668687, 2010). "Different mutations in the human FOXI1 gene and its regulatory binding site on SLC26A4 (also known as pendrin) have been shown to compromise the transcription of this anion transporter gene in patients with Pendred Syndrome and nonsyndromic enlargement of the vestibular aqueduct." (PMID 20809947, 2010).
Pendred syndrome (continued). "Mutations in SLC26A4 is very diverse in European and US populations without any prevalent mutations that account for more than 10% of the alleles in patients with Pendred syndrome or EVA." (PMID 19040761, 2008). "While our results suggest that SLC26A4-mediated HCO3– secretion would be beneficial for CF airways, other studies have implicated this transporter in fluid absorption, as shown in airway cells from patients with Pendred Syndrome, where the SLC26A4 gene is mutated, but CFTR is still active." (PMID 37967223, 2023). "HL-associated genes may present a phenotypic diversity as exemplified by the SLC26A4 mutations which can cause either Pendred Syndrome, or isolated HL with or without enlarged vestibular aqueduct (EVA)." (PMID 27941975, 2016). "Digenic inheritance of defects in SLC26A4 and EPHA2 has recently been reported in two Japanese Pendred syndrome cases." (PMID 34410491, 2022). "Pendred syndrome (PDS) and DFNB4 comprise a phenotypic spectrum of sensorineural hearing loss disorders that typically result from biallelic mutations of the SLC26A4 gene." (PMID 24860705, 2014). "Pathogenic variants in SLC26A4 can cause two related autosomal recessive disorders: non-syndromic enlarged vestibular aqueduct (NSEVA; MIM #600791) and Pendred syndrome (PDS; MIM #274600)." (PMID 40426046, 2025). "Additionally, digenic inheritance of SLC26A4 and EPHA2 in Pendred syndrome has been proposed and confirmed in two Japanese EVA families." (PMID 40225947, 2024). "However, about 50% of patients with Pendred syndrome are euthyroid, suggesting that SLC26A7 or another iodide transporter may compensate for the dysfunction of pendrin (SLC26A4)." (PMID 31372509, 2019). "Interestingly we detected no causative DEHAL1/IYD or SLC26A4/PDS variants, suggesting that these may be rarely responsible for CH due to DH, depending usually on iodine uptake or associated with syndromic features as in the case of Pendred syndrome." (PMID 33692749, 2020).
goiter (29 papers, 2004 to 2025). Enlargement of the thyroid gland usually caused by lack of iodine in the diet, hyperthyroidism, or thyroid nodules. "In our cohort, several affected children exhibited elevated serum thyroglobulin and goiter in the setting of pathogenic SLC26A4 variants, findings consistent with the interplay between genetic susceptibility and chronic iodine deficiency." (PMID 40956475, 2025). "We described a case involving concomitant mutations in the TG and SLC26A4 genes, resulting in fetal goiter and CH in a patient with PS." (PMID 41394090, 2025). "In this report we described concomitant mutations in the TG and SLC26A4 genes leading to fetal goiter and CH in a patient with PS." (PMID 41394090, 2025). "Fetal goiter is not a common clinical feature in PS, and in our case, the mutation in SLC26A4 seems to be more strongly linked to sensorineural deafness than to goiter." (PMID 41394090, 2025). "Defect in SLC26A4 cause loss of pendrin function, which results in defective iodide organification that induces thyroid overgrowth and goiter in most affected individuals." (PMID 26886089, 2016). "In this study, 8 patients had hearing loss and goiter and 4 of them carried homozygous or compound heterozygous SLC26A4 mutations." (PMID 22384008, 2012). "Pendred syndrome, a common autosomal-recessive disorder characterized by congenital deafness and goiter, is caused by mutations of SLC26A4, which codes for pendrin." (PMID 15320950, 2004). "Additionally, patients with a goiter with accompanying hypothyroidism have a swollen thyroid and SLC26A4 gene mutations." (PMID 38673775, 2024). "A combination of three parameters was suggested to define and diagnose PS: (i) sensorineural deafness with bilateral EVA; (ii) thyroid abnormality comprising goiter and/or hypothyroidism and/or a positive perchlorate discharge test; (iii) biallelic SLC26A4 mutations." (PMID 26886089, 2016). "Since environmental and other genetic factors may modulate the effects of SLC26A4 mutations on the development of goiter, the expression of goiter in PS patients is variable and may have incomplete penetrance." (PMID 19040761, 2008). "In addition, the common anion exchanger such as pendrin, which is encoded by Solute Carrier 26A4 (SLC26A4), could be defected in the patients with goiter and/or hypothyroidism." (PMID 33106572, 2020). "We did not observe differences in clinical features, including radiological findings, the presence of goiters, and audiological results, in our patients with different SLC26A4 genotypes." (PMID 31581539, 2019). "Slc26a4-/- mice are profoundly deaf with vestibular dysfunction, but they lack goiter and thyroid histological abnormalities." (PMID 21689387, 2011). "Clinically, patients with SLC26A4 mutations have been shown to demonstrate a broad-spectrum of phenotypes, ranging from non-syndromic isolated EVA to full-blown PS with goiter and incomplete partition of the cochlea in addition to EVA." (PMID 21811566, 2011). "Most patients with biallelic pathogenic variants in the SLC26A4 gene (75%) showed no signs of goiter." (PMID 36499699, 2022). "In countries with a high iodine intake, goiter development and thyroid dysfunction are usually not seen in patients with biallelic mutations in the SLC26A4 gene." (PMID 26886089, 2016). "In conclusion, the ICD did not induce goiter in Slc26a4-null mice whereas, in humans, SLC26A4 mutations sometimes lead to goiter and even hypothyroidism." (PMID 21689387, 2011). "SLC26A4 mutations associated with nonsyndromic sensorineural hearing loss with EVA showed partial transport function of pendrin, which may be sufficient to maintain thyroid function and eliminate goiter." (PMID 23151025, 2012). "None of the patients with SLC26A4 mutations or variants showed the presence of goiter." (PMID 19744334, 2009). "Deletion of Slc26a4 enhanced the increase in TSH and goiter development in mice." (PMID 38673775, 2024).
hypothyroidism (16 papers, 2011 to 2025). Abnormally low levels of thyroid hormone. "Mutation-induced deficiency of SLC26A4 induces hypothyroidism." (PMID 38673775, 2024). "Thus, Slc26a4 (−/−) mice displaying iodide deficiency are euthyroid, while Slc26a7 (−/−) mice show hypothyroidism with histological thyroid abnormalities." (PMID 31372509, 2019). "Hypothyroidism was not reported in our patients carrying SLC26A4 variants." (PMID 37108562, 2023).
autosomal recessive hearing loss (14 papers, 2012 to 2025). "Pathogenic variants in SLC26A4 have been associated with autosomal recessive hearing loss (arHL) and a unilateral or bilateral enlarged vestibular aqueduct (EVA)." (PMID 34410491, 2022). "In particular, we did not test the most frequently mutated genes in patients with autosomal recessive hearing loss, such as SLC26A4, USH2A, and MYO7A, because their large size would have made Sanger sequencing labour-intensive." (PMID 30344259, 2018). "We screened 160 unrelated Japanese with severe to profound recessive nonsyndromic hearing loss (ARNSHL) without GJB2 or SLC26A4 mutations, and 192 controls with normal hearing." (PMID 24053799, 2013). "However, some studies from the United States, Belgium, Northern Europe, and East Asia indicated that pathogenic variants in SLC26A4, MYO15A, OTOF, and CDH23 are probably the most common causes of autosomal recessive hearing loss, after the exclusion of variants in the DFNB1 locus." (PMID 39498320, 2024).
sensorineural hearing loss (12 papers, 2011 to 2022). "In an Slc26a4-insufficient mouse model of sensorineural hearing loss, macrophage activity is likely affecting hearing by influencing the function of the stria vascularis." (PMID 32194497, 2020). "There are reports of patients with sensorineural hearing loss caused by co-existing mutations in GJB2 or SLC26A4 and the mitochondrial gene, and one enlarged vestibular aqueduct syndrome patient with compound mutations in both SLC26A4 and GJB2 respectively." (PMID 26061099, 2015). "This study aims to investigate the mutation spectrum of GJB2, mitochondrial 12S rRNA, and SLC26A4 genes of Han Chinese, Hui people, and Uyghur ethnicities in sensorineural hearing loss (SNHL) patients in northwest of China." (PMID 24804242, 2014). "Mutations of the SLC26A4 (PDS) gene can cause sensorineural hearing loss with goiter (PDS) or non-syndromic recessive deafness with enlarged vestibular aqueduct." (PMID 21689387, 2011). "The low-frequency SLC26A4 mutation in Uyghur NSD patients is inconsistent with the fact that SLC26A4 is one of the major sensorineural deafness-associated genes." (PMID 21917135, 2011). "Thus, this study aimed to investigate and describe the prevalence of mutations in the SLC26A4 gene in nonsyndromic prelingual sensorineural hearing loss (SNHL) patients of a cohort from the Southeast of Brazil who had been previously tested for GJB2, GJB6, and MT-RNR1." (PMID 30068397, 2018). "We investigated the potential contribution of large SLC26A4 deletions and duplications to sensorineural hearing loss (SNHL) by screening 107 probands with one known SLC26A4 mutation by Multiplex Ligation-dependent Probe Amplification (MLPA)." (PMID 24860705, 2014). "This study aims to investigate the mutation spectrum of GJB2, mitochondrial 12S rRNA, and SLC26A4 genes of Han Chinese, Hui people, and Uyghur ethnicities in sensorineural hearing loss (SNHL) patients." (PMID 24804242, 2014).